GSTP1 (glutathione S-transferase pi 1)
Diseases named in the same sentence as GSTP1 in open-access papers (continued):
Sharing a sentence is not in itself a finding about the gene and the disease.
osteosarcoma (14 papers, 2013 to 2025). A usually aggressive malignant bone-forming mesenchymal neoplasm, predominantly affecting adolescents and young adults. "Genetic variants in ABCC3, ABCC5, FasL, GLDC and GSTP1 were repeatedly associated to osteosarcoma treatment outcome, using very heterogeneous efficacy outcomes." (PMID 36536332, 2022). "A significant correlation was also found between higher GSTP1 transcript levels and low growth inhibition following doxorubicin treatment in osteosarcoma xenografts, and poor histological response has been found to be increased in germ-line variants of GSTP1." (PMID 32961800, 2020). "The gene polymorphism GSTP1 rs1695 GG genotype and G allele has been more often found in osteosarcoma patients with poor response to chemotherapy, poor event-free survival, and poor overall survival." (PMID 32961800, 2020). "Overexpression of GSTP1 in the osteosarcoma cell line Saos-2 led to increased resistance to doxorubicin and cisplatin, and GSTP1 suppression in the HOS cell line caused more apoptosis and DNA damage in response to these drugs." (PMID 32961800, 2020). "In canines with osteosarcoma, higher GSTP1 expression was associated with significantly shorter median remission and survival times." (PMID 32961800, 2020). "In line with this, cisplatin resistance has been associated with increased levels and enzymatic activity of GSTP1 in osteosarcoma cell lines." (PMID 32961800, 2020). "The GSTP1 GG genotype was associated with poor OS, indicating the potential role of GSTP1 IIe105Val polymorphism in the individualized tailoring chemotherapy for osteosarcoma." (PMID 24353716, 2013). "The relationship of GSTM1, GSTT1 and GSTP1 gene polymorphisms with prognosis of osteosarcoma is shown in Table-III." (PMID 24353716, 2013). "The results of the present study support the pharmacogenetic role of GSTP1 IIe105Val polymorphism in patients with osteosarcoma treated with adjuvant chemotherapy." (PMID 24353716, 2013). "Individuals with GSTP1 G/G genotype tended to live shorter than A/A genotype and we found a significantly higher risk of death from osteosarcoma (adjusted HR=2.73, 95% CI=1.05-7.45)." (PMID 24353716, 2013). "Meta-analysis of data on osteosarcoma revealed that GSTP1 polymorphisms may be an important risk factor for osteosarcoma and that GSTP1 null genotype is associated with the higher risk of osteosarcoma." (PMID 40002376, 2025). "It has been shown that GSTP1 prevents irradiation-induced death of pancreatic cancer cells by inhibiting ferroptosis and the increased expression of this enzyme is associated with cancer risk and particularly with osteosarcoma." (PMID 40002376, 2025). "GSTP1 gene overexpression has been associated with poor response in osteosarcoma and other cancers." (PMID 37107591, 2023). "A previous study reported that the GSTP1 gene Ala114Val (rs1138272) polymorphism might be used as a predictive factor for cisplatin-based chemotherapy in osteosarcoma patients." (PMID 31528233, 2019). "Similarly, others have shown that the GSTP1 AA genotype also diminishes the risk of chemoresistance to doxorubicin in osteosarcoma patients." (PMID 26354850, 2015). "Furthermore, after the administration of DXR or cisplatin, glutathione-S-transferase P1 (GSTP1) levels were found to be elevated, and amplified GSTP1 expression in SAOS-2 cell lines from osteosarcomas was linked with heightened vulnerability to resistance to these two pharmaceutical reagents." (PMID 39015175, 2024). "One of the most recent studies, in which Asian osteosarcoma patients were analyzed, suggested that the GSTP1 gene polymorphism is associated with an increased risk of osteosarcoma, whereas the other GSTs gene polymorphisms may not influence the development of this cancer." (PMID 31357662, 2019).
osteosarcoma (continued). "In several tumor tissues, >90% of active GSTs is due to GSTP1 activity, which is highly expressed in various types of cancer, including osteosarcoma cells, whereas in healthy tissues, among them bone cells, osteocytes, GSTP1 expression is usually low." (PMID 40002376, 2025). "Our data suggest that ferroptosis induction in undifferentiated hBMSCs is primarily regulated by GPX4, whereas glutathione S-Transferase P1 (GSTP1) plays a key role in controlling ferroptosis in osteosarcoma cells." (PMID 40002376, 2025). "Another study found that GSTP1 expression was induced in osteosarcoma cell lines following treatment with doxorubicin or cisplatin." (PMID 32961800, 2020). "We assume that GSTP1 can protect osteosarcoma cells and increase their resistance to chemotherapy." (PMID 40002376, 2025). "However, in this case, we did not observe any induction of cell death by this substance, further supporting our conclusion that GSTP1 most likely plays an important role in the induction of cell death in osteosarcoma." (PMID 40002376, 2025). "Taken together, these findings support a role for GSTP1 in chemotherapy resistance in osteosarcoma and open up the possibility that targeting GSTP1 could be a useful therapeutic strategy especially in overcoming cisplatin resistance." (PMID 32961800, 2020). "The parallel overexpression of GSTP1-1 and efflux pumps may confer resistance to the tumor cells against chemotherapeutic drugs like cisplatin in osteosarcoma." (PMID 31357662, 2019). "In addition, MC3181 displayed a greater selectivity toward GSTP1-1, high cytotoxicity toward osteosarcoma cells, as well as a panel of different human melanoma cell lines, and exhibited a remarkable therapeutic activity against BRAF-V600E-mutant xenografts." (PMID 29358310, 2018). "Since activity of glutathione S-tranferase P1 (GSTP1) was demonstrated to be relevant for cisplatin resistance of U-2OS and Saos-2 osteosarcoma cells, we tested the efficacy of maltonis in presence of the GSTP1 inhibitor 6-(7-nitro-2,1,3-benzoxadiazol-4-ylthio)hexane (NBDHEX)." (PMID 24575739, 2014). "Furthermore, a study suggested that genetic variation of GSTP1 Ile105Val may be used as a prognostic factor to identify osteosarcoma patients who might benefit from chemotherapy." (PMID 31357662, 2019). "In addition, both authors’ microarray analyses exhibited GSTP1 and CYP4X1 genes responsible for cell detoxification, a drug chemoresistance mechanism in osteosarcoma." (PMID 37107591, 2023).
COVID-19 (12 papers, 2021 to 2025). A disease caused by infection with severe acute respiratory syndrome coronavirus 2. "A cross-country ecological study by Saadat (2020b) investigated the association between the GSTP1 Ile105Val polymorphism (rs1695) and COVID-19 prevalence and outcomes, using data from 45 nations." (PMID 41209585, 2025). "Haplotype analysis of GSTP1 genotypes revealed that carriers of H2 haplotype (presence of GSTP1 rs1695 variant allele and GSTP1 rs1138272 referent allele) exhibited the lowest risk of proneness to COVID-19." (PMID 36834445, 2023). "The association of GSTP1 polymorphisms with COVID-19 severity seems biologically plausible since GSTP1 is the most commonly expressed GST gene polymorphism outside the liver, with main expression in the heart, lung, and brain." (PMID 36834445, 2023). "The carriers of GSTM3* (rs1332018) and GSTP1* (rs1695) heterozygotes and GSTP1* (rs1138272) Val allele showed a reduced risk of developing COVID-19 as compared to the wild-type carriers." (PMID 37189435, 2023). "Individuals carrying the GSTP1* (Ile105Val rs1695) or GSTP1* (Ala114Val rs1138272) variants were less prone to develop COVID-19 as compared to the GSTP1 wild type genotypes." (PMID 37189435, 2023). "The data obtained herewith have shown that among examined polymorphisms, only GSTP1 haplotype (rs1695 and rs1138272) was associated with COVID-19 risk." (PMID 35361071, 2022). "The findings indicated that GSTM3 rs1332018 and GSTP1 rs1695 heterozygotes and carriers of the GSTP1 rs1138272 Val allele had decreased risk of developing COVID-19." (PMID 36009328, 2022). "Namely, the GSTP1 Val allele, which is shown to decrease the odds of developing severe COVID-19, decreases the probability of developing long-COVID myalgia in the present study." (PMID 35624818, 2022). "So far, GSTP1 variant alleles have been shown to affect the susceptibility and severity of COVID-19." (PMID 35624818, 2022). "Our latest findings showed that both genetic variants in GSTP1, Ile105Val (rs1695), and Ala114Val (rs1138272) are associated with susceptibility and severity of COVID-19." (PMID 35361071, 2022). "The results also align with reports that GSTP1 rs1695 Val allele frequencies are higher in countries with higher cases and increased COVID-19 mortality." (PMID 36009328, 2022). "Among six investigated GST polymorphisms, significant association between GST genotype and susceptibility for development of COVID-19 clinical manifestations was found for both GSTP1 (rs 1695 and rs1138272) and GSTM3 (rs1332018) polymorphisms." (PMID 34988113, 2021). "In a case–control study of 207 COVID-19 patients versus 252 matched controls, GSTP1 rs1695 (Ile105Val) variant carriers had significantly lower odds of developing COVID-19 (p = 0.002), while individuals with the GSTM3 CC genotype showed increased susceptibility (p = 0.024)." (PMID 41209585, 2025). "The presence of polymorphic allele of NR3C1 rs6198, ABCB1 rs2032582 or GSTP1 rs1695 polymorphism could predict poorer course of COVID-19 and also poorer treatment outcome." (PMID 39135792, 2024). "Concerning GSTP1 polymorphism, ecologic study indicates that countries with higher Val105 allelic frequency of the rs1695 polymorphism showed higher prevalence and mortality of COVID-19." (PMID 36834445, 2023). "Studies performed in a cohort of individuals of Serbian, Caucasian origin, revealed that individuals carrying the GSTP1-Val allele variant present lower odds of developing COVID-19; on the other hand, individuals carrying the GSTM3-CC allele variant present higher odds of developing COVID-19." (PMID 36834445, 2023). "Among three GST polymorphisms analysed in our study, the GSTP1 Ile/Val genotype was found to be associated with higher risk of developing a severe form of the disease in the population of vaccinated patients with COVID-19." (PMID 36834445, 2023).
COVID-19 (continued). "On the other hand, case–control study performed in a Caucasian population with Serbian origin revealed that individuals with heterozygous GSTP1 IleVal rs1695 genotype and individuals with at least one GSTP1* Val allele rs1138272 are less prone to develop COVID-19." (PMID 36834445, 2023). "GSTP1 Ile/Val genotype was found to be associated with a higher risk of developing a severe form of the disease in the population of vaccinated patients with COVID-19 (OR: 2.75; p = 0.0398)." (PMID 36834445, 2023). "Recently, it has been reported that the GSTP1-Ile105Val gene polymorphism is associated with increased morbidity and mortality in patients with COVID-19 and a higher incidence of GSTP1-Ile105Val gene polymorphism is directly proportional to mortality in different countries." (PMID 35371838, 2022). "Herein, we further substantiated results by haplotype analysis of GSTP1 genotypes and found that carriers of H2 haplotype (presence of GSTP1 rs1695 variant allele and GSTP1 rs1138272 referent allele) exhibited the lowest risk of susceptibility of COVID-19." (PMID 35361071, 2022). "Indeed, the data obtained showed that individuals carrying variant GSTP1-Val allele exhibit lower odds of COVID-19 development, contrary to the carriers of variant GSTM3-CC genotype who have higher odds for COVID-19." (PMID 34988113, 2021). "Our results on the association of GSTP1 polymorphisms with risk of COVID-19 seem biologically plausible since GST pi 1 (GSTP1) is highly expressed in lung tissue and might even be considered the predominant GST in the lungs." (PMID 34988113, 2021). "Similarly, morbidity and mortality of COVID-19 also correlate with GSTP1-Ile105Val polymorphism in a way that countries with more frequent Val105 allele have higher prevalence and mortality of COVID-19." (PMID 34988113, 2021). "Similarly, individuals with at least one GSTP1* Val allele rs1138272 had significantly lower odds of COVID-19 development (p < 0.05) compared to the carriers of wild-type GSTP1 AlaAla genotype." (PMID 34988113, 2021). "Indeed, the data obtained showed that individuals carrying variant GSTP1-Val allele exhibit lower odds of COVID-19 development (p = 0.002), contrary to carriers of variant GSTM3-CC genotype which have higher odds for COVID-19 (p = 0.024)." (PMID 34988113, 2021). "The cumulative effect of risk genotypes across GSTP1 and GSTM3 was significant, with the risk of developing COVID-19 rising with each additional risk genotype." (PMID 40867811, 2025). "Variants such as SOD2 rs4880, GSTP1, GSTO1, PON1, and NOS3 have been associated with reduced enzymatic activity, impaired detoxification of ROS, and worsened COVID-19 severity or post-acute sequelae." (PMID 41209585, 2025). "Our findings bring novel evidence of NR3C1 rs6198, GSTP1 rs1695, and CYP3A4 rs35599367 polymorphisms having impact on COVID-19 severity, the course of the disease, and the outcome of treatment with dexamethasone and methylprednisolone." (PMID 39135792, 2024). "A study in patients with COVID-19 ranging in age from 20 to 58 years showed a decrease in the GSTp1 and there was a correlation with a higher prevalence of deaths in males in comparison with female patients." (PMID 37111348, 2023). "The combined GSTP1* and GSTM3* polymorphisms showed a cumulative risk regarding COVID-19 prevalence and severity." (PMID 37189435, 2023). "The results indicated a significant association between GSTP1 and GSTM3 polymorphisms and COVID-19 susceptibility and clinical manifestation." (PMID 37189435, 2023). "Combined GSTP1 (rs1695 and rs1138272) and GSTM3 genotype exhibited cumulative risk with regard to both COVID-19 occurrence and severity." (PMID 36834445, 2023). "Concisely, COVID-19 patients with GSTT1-null genotype exhibit higher mortality and according to our latest results, GSTP1 (rs1695 and rs1138272) polymorphisms influence susceptibility and severity of COVID-19." (PMID 35361071, 2022).
COVID-19 (continued). "GSTM1 and GSTT1 gene deletions as well as GSTP1 rs1138272 and rs1695, GSTA1 rs3957357, and GSTM3 rs1332018 polymorphisms have been investigated in a cohort of 207 COVID-19 patients and 252 healthy individuals of Serbian, Caucasian origin." (PMID 36009328, 2022). "Taken together, our results on the association between certain GSTP1 and GSTM3 genetic variants and COVID-19 have shed some light on the involvement of genetic susceptibility in COVID-19 development." (PMID 34988113, 2021). "Among six GST polymorphisms analyzed in this study, GSTP1 rs1695 and GSTM3 were found to be associated with COVID-19." (PMID 34988113, 2021). "It is noteworthy to mention that, apart from its well-established role in detoxification and antioxidant protection, GSTP1 also exhibits leukotriene synthase activity, thus influencing pulmonary and extrapulmonary manifestations of COVID-19." (PMID 34988113, 2021). "The potential effect of GSTP1 in COVID-19 should also be analyzed in line with its anti-inflammatory role." (PMID 34988113, 2021). "Namely, we observed that individuals with GSTP1 IleVal rs 1695 genotype were almost 3-fold less prone for COVID-19 development (OR = 0.33, 95%CI = 0.17–10.67, p = 0.002) in comparison to the carriers of wild-type GSTP1 IleIle genotype." (PMID 34988113, 2021). "Namely, carriers of heterozygous GSTP1 IleVal rs1695 genotype are less prone to develop COVID-19 (OR = 0.66, 95%CI = 0.44–0.98, p = 0.042)." (PMID 34988113, 2021). "Among six GST polymorphisms analyzed in this study, GSTP1 rs1695 and GSTM3 rs1332018 were found to be associated with COVID-19." (PMID 34988113, 2021). "Moreover, combined risk genotypes across GSTP1 and GSTM3 conferred higher risk for both incidence and severity of COVID-19 (p = 0.001 and p = 0.025, respectively)." (PMID 41209585, 2025). "Furthermore, combined GSTP1 (rs1695 and rs1138272) and GSTPM3 genotype showed cumulative risk regarding both COVID-19 prevalence and severity." (PMID 36834445, 2023). "Moreover, combined GSTP1 (rs1138272 and rs1695) and GSTM3 genotype exhibited cumulative risk regarding both COVID-19 occurrence and COVID-19 severity (p = 0.001 and p = 0.025, respectively)." (PMID 34988113, 2021). "Moreover, combined GSTP1 (rs1138272 and rs1695) and GSTM3 genotype exhibited cumulative risk regarding both COVID-19 occurrence and COVID-19 severity." (PMID 34988113, 2021). "Indeed, we found that the polymorphisms in GSTP1, GSTM3, GSTO1 and GSTO2 genes were associated with significant odds of COVID-19 development, while the combined GSTP1 and GSTM3 genotype even exhibited cumulative risk regarding both COVID-19 occurrence and COVID-19 severity." (PMID 35624818, 2022). "This leads us to think about the role of using GSTp1 (glutathione S-transferase-pi), a cytosolic detoxification enzyme, and SOD3 (extracellular superoxide dismutase-ECSOD) in COVID-19 disease management." (PMID 35314591, 2022). "Further pointing to the multifaceted role of GSTP1 as the dominant glutathione transferase class in lungs are the results regarding the role of combined GSTP1 (rs1138272 and rs1695) and GSTM3 genotype in both COVID-19 occurrence and severity." (PMID 34988113, 2021). "The distribution of polymorphisms in cytosolic glutathione S-transferases GSTA1, GSTM1, GSTM3, GSTP1 (rs1695 and rs1138272), and GSTT1 were assessed in 207 COVID-19 patients and 252 matched healthy individuals, emphasizing their individual and cumulative effect in disease development and severity." (PMID 34988113, 2021).
glioblastoma (12 papers, 2004 to 2025). The most malignant astrocytic tumor (WHO grade IV). "C/EBPβ is a crucial transcription factor that responds to ROS and regulates the expression of NQO1 and GSTP1, which help neutralize ROS in glioblastoma cells." (PMID 41009025, 2025). "We found that the more acidic form of GSTP1 was reduced in glioblastomas treated with PF4-DLR for 10 days." (PMID 21060779, 2010). "Kecheng Lei shows that MNPC, a small molecule NQO1 and GSTP1 dual inhibitor, can reduce ROS reaction via inhibiting both NADPH quinone oxidoreductase 1 (NQO1) and GSTP1, leading to apoptosis and mitigated glioblastoma (GBM) cell proliferation." (PMID 34238333, 2021).
non-small cell lung carcinoma (12 papers, 2016 to 2025). A group of at least three distinct histological types of lung cancer, including non-small cell squamous cell carcinoma, adenocarcinoma, and large cell carcinoma. "An in vitro study demonstrated that enzyme activity in a GSTP1 variant, Val105, was reduced by 80%, and this variant exhibited better survival than the wild type genotype in patients with non-small-cell lung carcinoma after platinum-based chemotherapy." (PMID 34209254, 2021). "In our study, we found only 10.6% of variant alleles of GSTP1 Ile105Val, contrary to the other report in Thai non-small cell lung cancer patients which variant allele frequency were reported as 26.1%." (PMID 32711417, 2020). "However, many studies were not in agreement about the GSTP1 methylation frequency in cancerous tissue of non-small cell lung cancer patients respect adjacent benign tissue." (PMID 31357662, 2019).